IL12B (interleukin 12B)
Diseases named in the same sentence as IL12B in open-access papers (continued):
Sharing a sentence is not in itself a finding about the gene and the disease.
psoriasis (continued). "For the IL12B SNPs, the effect sizes in patients with type 1 PsA were similar to those in patients with type 1 psoriasis (for rs3212227, OR 1.4; for rs6887695, OR 1.3), supporting the hypothesis that the association is primarily with psoriasis." (PMID 19035472, 2008). "Despite this, it contradicts the therapeutic purpose of IL12B-targeting monoclonal antibody ustekinumab in treating psoriasis and psoriatic arthritis by reducing IL12B signaling." (PMID 39932908, 2025). "Among inflammatory dermatoses, psoriasis exhibits the strongest overlap with dementia genetics, with shared susceptibility loci including APOE, IL12B, and HLA-DRB5, and transcriptional regulators such as ZNF384 that converge on IL-17/TNF signaling." (PMID 41465136, 2025). "The therapeutic importance of IL12B in psoriasis was highlighted by early clinical trials that targeted its encoded p40 subunit, common to IL-12 and IL-23." (PMID 41465136, 2025). "A meta-analysis identified 11 susceptibility loci shared between psoriasis and IBD, but only four—IL23R, IL12B, REL, and TYK2—showed strong overlap for CD, suggesting weaker genetic linkage compared with UC." (PMID 41153620, 2025). "Furthermore, IL-12B (also known as IL-12p40) has been linked to genetic susceptibility, increased expression, and a pro-inflammatory role in other autoimmune diseases such as psoriasis and multiple sclerosis, further supporting its contribution to the inflammatory milieu in MG." (PMID 40831557, 2025). "Furthermore, the role of specific SNPs like IL-12B and IL-23R in psoriasis predisposition, and their influence on cytokine synthesis and T-cell differentiation, can provide a genetic framework that, when altered, may shift the therapeutic response spectrum of UST." (PMID 38256367, 2024). "The link between psoriasis (PSORS11) and IBD (IBD19) with locus 5q33.1 is well documented, particularly regarding the polymorphisms of the IL12B gene (also known as IL-23B or p40)." (PMID 39364475, 2024). "Psoriasis has been linked to genes that encode components of the IL-23/IL-12 pathways, including IL23R and IL12B." (PMID 39188726, 2024). "This inhibition resulted in a significant decrease in key inflammatory cytokines (Il1b, Il6, Il12b, Il17a, Il22, and Tnf) that are critical in psoriasis’ pathogenesis." (PMID 39335596, 2024). "Furthermore, the rs3212227 SNP in the IL12B gene, characterized by a substitution of thymine (T) with cytosine (C), is associated with psoriasis susceptibility by upregulating IL12B expression, which contributes to the dysregulated immune response observed in psoriasis." (PMID 37569685, 2023). "Patients with the genotype of TG at rs3212227 (IL-12B) were more sensitive to using acitretin in the treatment of psoriasis." (PMID 35814239, 2022). "Patients with the genotype of TG (χ2 = 6.124, p = 0.035) at rs3212227 (IL-12B) were more sensitive to using acitretin in the treatment of psoriasis." (PMID 35814239, 2022). "IL-12B protects against psoriasis and psoriatic arthropathy, LAP-TGF-β-1 protects against osteoarthritis, TWEAK protects against asthma, VEGF-A protects against ulcerative colitis, and LT-α protects against both type 1 diabetes and rheumatoid arthritis." (PMID 34878845, 2021). "For IL-12B, we found a protective effect of elevated biomarker levels against developing psoriasis and psoriatic arthropathy." (PMID 34878845, 2021). "Ustekinumab is an anti‐IL12B monoclonal antibody used to treat psoriasis and has since been successfully repurposed to treat Crohn's disease." (PMID 33748968, 2021). "For IL-12B, we found protective effects against psoriasis [odds ratio (OR) = 0.84, 95% confidence interval (CI) = 0.80 to 0.88; fig." (PMID 34878845, 2021). "For example, we provide supporting evidence for a role of IL4R in asthma, IL2RA in thyroid dysfunction, and IL12B in psoriasis, as well as many cellular phenotypes, such as Transferrin receptor protein 1 (encoded by TFRC) in mean corpuscular hemoglobin." (PMID 32628676, 2020).
psoriasis (continued). "Genetic variability in the area of IL12B and IL17RA has previously been associated with psoriasis in many studies." (PMID 31211819, 2019). "In conclusion, this study confirms that two SNPs in the IL12B and TNF genes are associated with susceptibility to psoriasis in Danish patients with moderate-to-severe psoriasis." (PMID 29389950, 2018). "Many genes (e.g., IL-12B, IL-23A, IL-23R, TRAF3IP2, and TYK2) are significantly associated with psoriasis." (PMID 29292715, 2017). "The C/C genotype in the IL12B gene is a protective factor of psoriasis (P = 0.0218; OR = 0.51; 95% CI: 0.27–0.96) in Chinese." (PMID 24971308, 2014). "We genotyped seven single-nucleotide polymorphisms (SNPs) in candidate genes of six ILs: IL4, IL10, IL12B, IL13, IL15, and IL23R, which have been shown in the literature to be associated with psoriasis in other ethnic groups." (PMID 24971308, 2014). "Initial causative research has identified strong association between psoriasis and the interleukin genes (IL4, IL10, IL12B, IL13, and IL23R) in the northern European from US and UK." (PMID 24971308, 2014). "A GWAS performed in a Chinese population (217 cases and 288 controls) identified other polymorphisms associated with psoriasis in IL23R (A allele rs11465817-A allele rs1343152 haplotype) and IL12B (rs6887695)." (PMID 24069534, 2013). "Nevertheless, 7 of the PP-increased DEGs were associated with psoriasis susceptibility loci (LCE3D, IFIH1, GRHL3, IL12B, PRSS53, REL and NOS2), and 1 PP-decreased DEG was near a psoriasis susceptibility locus (SDC4)." (PMID 24260178, 2013). "To investigate the therapeutic applicability of targeting IL-12B mRNA in psoriasis, we employed the psoriasis xenograft transplantation model." (PMID 21352568, 2011). "The associated variant within IL12B, rs3212227, is located in the 3′ UTR region, and the SLE risk allele is the same as previously reported for psoriasis." (PMID 22046141, 2011). "shRNA-expressing lentiviral vectors are intradermally injected in xenografted psoriatic skin and the effects of the treatment evaluated by clinical psoriasis scoring, by measurements of epidermal thickness, and IL-12B mRNA levels." (PMID 21352568, 2011). "To evaluate the effects of targeting IL-12B mRNA in psoriatic skin by RNA interference, we wished to employ the psoriasis xenograft transplantation model in which psoriatic skin is grafted onto the back of SCID mice." (PMID 21352568, 2011). "There was a statistically significant difference between PsA and psoriasis alone at three loci (HLA-C, IL-12B and IL-23R)." (PMID 20606885, 2010). "In this large case–control study, we observed that polymorphisms in the IL12B and IL23R genes, both of which were previously associated with psoriasis, are also associated with susceptibility to PsA." (PMID 19035472, 2008). "Key genetic loci such as HLA-C, TNIP1, IL12B, and IL23R are linked to psoriasis." (PMID 40557155, 2025). "Although clinically distinct, psoriasis and IBD share core pathogenic mechanisms, including immune dysregulation, Th17-mediated inflammation, and overlapping susceptibility loci such as IL23R and IL12B." (PMID 41153620, 2025). "In addition, several genetic studies have identified multiple susceptibility loci for psoriasis, including psoriasis susceptibility region 1 (PSORS1), IL12B, and the vitamin D receptor (VDR) gene." (PMID 41465136, 2025). "The balance between Th17 and regulatory T-cells (Treg) is also altered in psoriasis, where Treg develop expression of RORγt and become functionally impaired; this can be partially explained by polymorphisms in genes such as TNF, IL12RB2, and IL12B." (PMID 38256115, 2024). "In addition, the genes encoding proteins involved in the nuclear factor κB (NFκB) signaling pathway, including interleukin 12B (IL12B), IL23A, and tyrosine kinase 2 (TYK2), have also been reported as susceptibility genes for psoriasis." (PMID 37511476, 2023).
psoriasis (continued). "Certain genes, like HLA-C, IL23R, IL12B, and LCE3B/3C, increase susceptibility to psoriasis." (PMID 38022642, 2023). "Herein, we found serum levels of IL-12B (median: 6.16 vs. 9.03, p = 0.0194) and Th17 cytokines (IL-17A: median: 0.32 vs. 1.05, p = 0.0026; IL-22: median: 4.41 vs. 4.41, p = 0.0120) were increased in psoriasis patients." (PMID 36118416, 2022). "However, reduction of IL-12B signaling is the therapeutic aim of the IL-12B–targeting monoclonal antibody ustekinumab, which is used to treat symptoms of both psoriasis and psoriatic arthropathy." (PMID 34878845, 2021). "Genetic alterations in IL12B may influence the response to biologics indicated for the treatment of moderate-to-severe psoriasis, especially UTK, an IL-12/23 inhibitor." (PMID 33921427, 2021). "This interaction could potentially lower the IL12B expression and thus alleviate inflammatory processes during psoriasis." (PMID 31211819, 2019). "The C/C genotype for rs3212227 in IL12B is a protective factor (OR = 0.51) from psoriasis." (PMID 24971308, 2014). "However, with respect to two other psoriasis susceptibility loci (rs1008953/SDC4 and rs2082412/IL12B), risk alleles were enriched in subjects with IL-13-weak patterns (Cliff's delta ≥0.25; P≤0.045; FDR-adjusted P≤0.40)." (PMID 22479649, 2012). "The p40 subunit is a clinically validated therapeutic target in psoriasis, but it remains unclear if targeting IL-12B mRNA by RNAi-mediated degradation is therapeutically relevant." (PMID 21352568, 2011). "However, in contrast to local anti-TNFα treatment, the therapeutic potential of targeting IL-12B at the RNA level in psoriasis is questioned." (PMID 21352568, 2011). "Using the psoriasis xenograft transplantation model, we wished to evaluate if lentiviral delivery of shIL12B #6 could lower IL-12B mRNA levels and if this would have a beneficial effect on the disease phenotype." (PMID 21352568, 2011). "For example, CXCR4 gene which contributes to the pathways driven by IL12B gene was not previously associated with psoriasis susceptibility in single-marker GWAS but was being implicated as part of the central mechanisms of disease pathophysiology using genome-wide pathway analysis." (PMID 31130981, 2019). "The possibility that inclusion of RF-positive patients in the current series may have diluted the observed effect of the IL12B and IL23R variants in PsA susceptibility should be considered, particularly because some of these patients may be found to have RA with coincidental psoriasis." (PMID 19035472, 2008). "Hence, the IL23R and IL12B loci appear to be associated with psoriasis and PsA but not with inflammatory arthritis in the form of RA." (PMID 19035472, 2008). "Proteins related to the central disease‐driving pathways of psoriasis, namely the TH1 (CCL3, CCL4, CXCL9, CXCL10, CXCL11, TNFα) and TH17 pathway (CXCL1, CCL20, IL‐17A, IL‐12B) were found elevated in lesional skin across both studies." (PMID 40970551, 2025). "Genome-wide association studies (GWAS) have identified numerous shared genetic regions between IBD and psoriasis, particularly highlighting key loci such as IL23R, IL12B, REL, and tyrosine kinase 2 (TYK2)." (PMID 39463646, 2024). "There also exists common genetic abnormalities (chromosomal locus 6p21, IL23R, and IL12B), immune dysfunction, and inflammation (IL17), or gut dysfunction of disease progression both in both psoriasis and ulcerative colitis." (PMID 36106326, 2022). "Seven of these have previously been reported for psoriasis (MHC, TRAF3IP2, IL12B, IL23R, IL23A-STAT2, TNIP1, TYK2)." (PMID 25651891, 2015).
psoriasis (continued). "Recently, a genome-wide scan study in 1,409 psoriasis cases and 1,436 controls revealed associations between three genes of the IL-23 pathway (IL23A, IL23R and IL12B), two genes of nuclear factor-κB (NF-κB) pathway (TNIP1 and TNFAIP3) and psoriasis." (PMID 21555979, 2011). "Of considerable interest, the correlation matrix revealed a distinct cytokine panel where cytokines (IFN-γ, IL-18, TNF-α, IL-12B, IL-17A, IL-17F, and IL-22) were positively correlated with each other in psoriasis patients but not in healthy controls." (PMID 36118416, 2022). "In particular, serum levels of IL-17A were strongly correlated with IL-1α, IL-15, IFN-γ, IL-18, TNF-α, IL-12B, IL-17F, and IL-22 in psoriasis but not in healthy controls." (PMID 36118416, 2022). "In lesional skin of patients with psoriasis, p35 (IL-12A) transcripts were not increased, whereas p40 (IL-12B) and p19 (IL-23A) transcripts were increased." (PMID 36110854, 2022). "Across five patients with psoriasis, we reported a sub-cluster of DCs (IRF4+ cDC2) that displays elevated expression of CCL17, CCL22, and IL12B, markers of cDC2s that have recently been shown to drive psoriatic inflammation in mice and humans through the recruitment of inflammatory T cells." (PMID 33053333, 2020). "Several cytokine genes with overall low expression but high differential effect in psoriasis (IFNG, IL12B, IL17F, and IL22) displayed higher magnitude changes with cDNA than with cRNA hybridization, whereas the highly expressed gene IL1F9 showed a higher magnitude change with cRNA hybridization." (PMID 23308107, 2013). "Indeed, a recent study of UK patients with psoriasis demonstrated ORs of 1.67, 1.98, 1.38, and 1.72 for the rs11209026 and rs7530511 IL23R SNPs and the rs3212227 and rs6887695 IL12B SNPs, respectively." (PMID 19035472, 2008). "However, the psoriatic phenotype was not significantly affected by targeting IL-12B mRNA in the psoriasis xenograft transplantation model." (PMID 21352568, 2011).
asthma (20 papers, 2006 to 2025). "We are interested in the association between IL-12A and IL-12B genotypes and asthma-relevant phenotypes." (PMID 28600552, 2017). "In this hospital-based case-control study, we investigated the association of IL-12A rs568408, IL-12A rs2243115 and IL-12B rs3212227 polymorphisms and risk of asthma in Taiwan." (PMID 28600552, 2017). "The aim of this study was to investigate the association of polymorphisms in IL-12A/IL-12B with asthma." (PMID 28600552, 2017). "In the results, the authors showed that one of the alleles of the IL12B gene was under-transmitted to children with asthma." (PMID 24260251, 2013). "IL-12B is located in this genomic region and encodes IL-12p40; however, the allelic effects of this polymorphism on asthma susceptibility and asthma-related phenotypes has been shown." (PMID 21612588, 2011). "The 5q23.2-q34 region contains the cytokine gene cluster (IL4, Il13, IL5, IL12B) and has previously been suggested as an asthma/atopy susceptibility locus and the 7p21.1-14.1 region contains the previously identified asthma susceptibility gene, GPRA (7p14.3)." (PMID 18442398, 2008). "In addition, IL-12B is linked to various pathogenic inflammatory responses, including silicosis, graft rejection, and asthma." (PMID 40261473, 2025). "IL12B encodes a subunit of two cytokines (IL-12 and IL-23) involved in the immune response and airway hyperresponsiveness, whose expression levels have been related to the response to corticosteroids in bronchial biopsies from asthma patients." (PMID 32326339, 2020). "Thus, it is worthwhile for scientists to investigate the gene-gene interaction between IL-12A and IL-12B and their possibility to be novel determinants for asthma susceptibility, as is the case for cancer genomic etiology." (PMID 28600552, 2017). "In 2011, Chen and colleagues reported that IL-12A rs568408 and IL-12B rs3212227 SNPs may individually and jointly contribute to asthma risk in a moderate population, 197 asthma patients and 369 controls in mainland China23." (PMID 28600552, 2017). "Therefore, in the current study, IL-12A rs568408, IL-12A rs2243115, and IL-12B rs3212227 polymorphisms were selected to investigate the associated risk of asthma in Taiwan, and their associations with clinical features, such as symptoms severity." (PMID 28600552, 2017). "IL12B may be an important asthma gene and an IL12B promoter polymorphism is associated with the severity of atopic and non-atopic asthma in children." (PMID 26986948, 2016). "IL12B, (rs6887695), has also been associated with another immune disorder, asthma." (PMID 24352087, 2013). "Some CARD15 variants had an asthma protective effect while IL12B SNPs carried risk alleles." (PMID 16600026, 2006). "However, there are only limited studies to date that have examined the association between IL-12B genotypes and asthma risk, and the contribution of IL-12A genotypes to asthma is largely unknown." (PMID 28600552, 2017). "It turned out that the mRNA expressions of several inflammatory factors, such as tumor necrosis factor (TNF), Muc5ac, IL-4, IL-13, and IL-12b were significantly upregulated in asthma group compared with control and diacerein groups." (PMID 33013396, 2020). "OfHz stimulation induced IL-12b, IL-10 expression by immature DC and potentiated LPS-induced expression and production of IL-10 and IL-12β by human DCs in the BA asthma group." (PMID 31750318, 2019). "Further SNPs in DPP10, IL12B and IL4 were now found to be associated with asthma in our population, but only at the nominal significance level of 0.05." (PMID 21103062, 2010). "We found that SNPs at IL-12A rs568408, but not IL-12A rs2243115 or IL-12B rs3212227, were genomic determinants for asthma risk." (PMID 28600552, 2017). "By contrast, neither the G allele of IL-12A rs2243115 nor the C allele of IL-12B rs3212227 was associated with any significantly increased risk of asthma." (PMID 28600552, 2017).
asthma (continued). "Knockout of the FTO gene in mouse lung tissue cells resulted in significant asthma-like inflammation in mice, as evidenced by upregulation of Th2 cell marker IL13 mRNA levels and downregulation of Th1 cell marker IL12b and the T cell antibody CD8b1." (PMID 39108751, 2024). "At least one positive SNP with a TDT of p < 0.05 for asthma or total IgE and calcidiol or calcitriol was seen in IL10, GC, IL12B, CYP2R1, IL4R, and CYP24A1." (PMID 16600026, 2006). "SNPs in 5 genes showed a p-value < 0.05 with asthma (IL10, IL12B, VDR, CARD15 and CYP24A1)." (PMID 16600026, 2006).